CCDC148 (coiled-coil domain containing 148)
Synonyms: MGC125588
Tractability: No criterion of Open Targets' tractability assessment is met for any kind of drug.
Gene: Protein-coding gene on chromosome 2 (158,171,073 to 158,456,753, reverse strand). Ensembl gene ENSG00000153237.
Subcellular location (Human Protein Atlas): Nucleoli; Nucleoli rim; Nucleoplasm
Gene Ontology:
Molecular function: protein binding
Genetic constraint (gnomAD): Loss-of-function variants: 65 observed, 66.09 expected, observed/expected ratio (o/e) 0.98, 90% interval 0.8 to 1.21. The upper end of that interval is the gene's LOEUF score, 1.21, which puts it in group 5 of 6, group 1 being the genes least tolerant of losing a copy. Missense variants: 546 observed, 548.34 expected, observed/expected ratio (o/e) 1, 90% interval 0.93 to 1.07. Synonymous variants: 189 observed, 183.14 expected, observed/expected ratio (o/e) 1.03, 90% interval 0.92 to 1.16.
Homologues: Orthologues: chimpanzee CCDC148 (98% identical), macaque CCDC148 (93% identical), dog CCDC148 (83% identical), guinea pig CCDC148 (73% identical), rat Ccdc148 (73% identical), mouse Ccdc148 (72% identical), tropical clawed frog ccdc148 (51% identical). Paralogues in human: CCDC112 (15% identical).
Diseases named in the same sentence as CCDC148 in open-access papers:
CCDC148 is named in the same sentence as 8 diseases in open-access papers, as found by Europe PMC text mining. Sharing a sentence is not in itself a finding about the gene and the disease. The quoted sentences say what the papers report.
pancreatic cancer (1 paper, 2021). "A novel 14-gene signature comprising CCDC148, SH3RF2, CACNA1D, POLD3, PARP1, AP1M2, C4orf19, ANO1, VGLL1, SCEL, INPP4B, NET1, INSIG2 and BVES and a corresponding risk score formula were established for pancreatic cancer risk stratification and prognosis prediction." (PMID 33731794, 2021).
Tumor (2 papers, 2024 to 2025). "Risk score = 0.268 ∗ P4HA1 - 0.168 ∗ CCDC148 + 0.094 ∗ UCA1 + 0.054 ∗ TMPRSS11E + 0.31 ∗ Tumor Stage." (PMID 41080752, 2025).
CCDC148 also shares sentences with these, for which no sentence is quoted: ovarian carcinoma (2 papers); cancer (1); cardiomyopathy (1); heart failure (1); neurodegenerative disease (1); Ventricular arrhythmia (1).